TMC7 (transmembrane channel like 7)
Description:
Acts as an inhibitory modulator of PIEZO2 mechanosensitive channel in dorsal root ganglion (DRG) neurons through physical interactions or interference with the interaction between PIEZO2 and the cytoskeleton.
Synonyms: FLJ21240
Tractability: Antibody: UniProt predicts a signal peptide or a membrane-spanning region; its Gene Ontology location is reachable by antibodies, with medium confidence. PROTAC: ubiquitination databases record sites on it.
Gene: Protein-coding gene on chromosome 16 (18,983,934 to 19,063,942, forward strand). Ensembl gene ENSG00000170537.
Subcellular location: Membrane
Subcellular location (Human Protein Atlas): Vesicles
Gene Ontology:
Molecular function: ion channel inhibitor activity; mechanosensitive monoatomic ion channel activity
Biological process: sensory perception of mechanical stimulus; monoatomic ion transmembrane transport
Cellular component: neuronal cell body; plasma membrane; membrane
Genetic constraint (gnomAD): Loss-of-function variants: 49 observed, 78.18 expected, observed/expected ratio (o/e) 0.63, 90% interval 0.5 to 0.8. The upper end of that interval is the gene's LOEUF score, 0.8, which puts it in group 3 of 6, group 1 being the genes least tolerant of losing a copy. Missense variants: 765 observed, 871.25 expected, observed/expected ratio (o/e) 0.88, 90% interval 0.83 to 0.93. Synonymous variants: 331 observed, 329.91 expected, observed/expected ratio (o/e) 1, 90% interval 0.92 to 1.1.
Homologues: Orthologues: macaque TMC7 (98% identical), chimpanzee TMC7 (97% identical), dog TMC7 (92% identical), pig TMC7 (91% identical), rat Tmc7 (91% identical), mouse Tmc7 (91% identical), rabbit TMC7 (90% identical), guinea pig TMC7 (81% identical), tropical clawed frog tmc7 (57% identical), Caenorhabditis elegans tmc-1 (24% identical), Caenorhabditis elegans tmc-2 (22% identical). Paralogues in human: TMC4 (36% identical), TMC8 (31% identical), TMC3 (25% identical), TMC5 (24% identical), TMC2 (23% identical), TMC6 (23% identical), TMC1 (21% identical).
Diseases named in the same sentence as TMC7 in open-access papers:
TMC7 is named in the same sentence as 10 diseases in open-access papers, as found by Europe PMC text mining. Sharing a sentence is not in itself a finding about the gene and the disease. The quoted sentences say what the papers report.
pancreatic cancer (4 papers, 2021 to 2023). "TMC7 was identified as a potential prognostic biomarker for pancreatic cancer, and its high expression was associated with a poor prognosis." (PMID 37468683, 2023). "Specifically, it has been suggested that the expression of Tmc7 is enhanced at the onset of pancreatic cancer; therefore, it is expected to be a biomarker at the onset of pancreatic cancer." (PMID 36451105, 2022). "TMC5 promotes prostate cancer cell proliferation and TMC7 is upregulated in cases with onset of pancreatic carcinoma." (PMID 34429071, 2021). "The AS events of TMC7 and CHECK1 were associated with liver metastasis in pancreatic cancer." (PMID 36713450, 2022). "Additionally, the knockdown of exon 17 of TMC7 significantly inhibited the proliferation, invasion, and migration of pancreatic cancer cells in 2D and 3D cell experiments." (PMID 36713450, 2022). "We evaluated the expression of TMC7 and CHEK1 AS events in pancreatic cancer cell lines and normal pancreatic cell lines by qRT-PCR." (PMID 36713450, 2022).
hepatocellular carcinoma (2 papers, 2021 to 2024). A malignant tumor that arises from hepatocytes. "In the meantime, TMC7 was identified as a potential prognostic biomarker for pancreatic cancer; the same association was discovered between TMC8 and hepatocellular carcinoma (HCC), TMC4, and breast cancer, TMC3 and colorectal cancer (CRC), TMC8 and head and neck squamous cancer." (PMID 35096973, 2021).
Infertility (1 paper, 2024). "To determine the cause of infertility in Tmc7–/– mice, we examined the composition of cell types in seminiferous tubules and cauda epididymis sections using hematoxylin staining in mouse testes at different developmental stages." (PMID 39269275, 2024). "Subsequently, Golgi-derived proacrosomal vesicles are unable to fuse with the developing acrosome and acrosome biogenesis is severely impaired, and thus TMC7-deficent male mice are completely infertile." (PMID 39269275, 2024).
male infertility (1 paper, 2024). The inability of the male to effect fertilization of an ovum after a specified period of unprotected intercourse. "By generating Tmc7 conventional knockout mice (Tmc7–/–), we demonstrate that TMC7 deficiency leads to aberrant Golgi morphology and impaired fusion of Golgi-derived vesicles to the acrosome, thus resulting in male infertility with an oligo-astheno-teratozoospermia (OAT) phenotype." (PMID 39269275, 2024). "Tmc7 expression is confined to the testis, and its deletion leads to male infertility." (PMID 39269275, 2024). "In this study, we demonstrated that Tmc7 was predominantly expressed in testes, and by generating knockout mice lacking TMC7 we found that TMC7 deficiency resulted in complete male infertility with an OAT-like phenotype." (PMID 39269275, 2024).
psychosis (1 paper, 2019). "Finally, Dbp, Paqr5, Ptprb, and Tmc7 are involved in the regulation of circadian rhythm, progesterone signaling, repression of EGFR signaling pathways, and psychosis risk, respectively." (PMID 31164799, 2019).
teratozoospermia (1 paper, 2024). "Tmc7−/− mice exhibited abnormal sperm head, disorganized mitochondrial sheaths, and reduced number of elongating spermatids, similar to human oligo-astheno-teratozoospermia." (PMID 39269275, 2024).
tumor (5 papers, 2016 to 2023). "HCC tumor tissues contain high levels of HMOX1, S100A9, TMC7, TRAF3 and TRIM21, whereas the expression of IL8RAP and RGL4 were higher in the control group." (PMID 37171396, 2023). "In fact, lncRNA MIR4713HG acted as a pro-tumor factor facilitating cell proliferation and metastasis of TSCC via the let-7c-5p/TMC7 signaling pathway, suggesting MIR4713HG might serve as a promising therapeutic target in TSCC." (PMID 37232821, 2023). "AS events of TMC7 and RHBDL2 showed higher expression in the primary PDAC tumor without liver metastasis." (PMID 36713450, 2022).
cancer (3 papers, 2021 to 2023). A tumor composed of atypical neoplastic, often pleomorphic cells that invade other tissues. "The exact role of IL18RAP, RGL4 and TMC7 in cancer and its potential as a therapeutic target or marker is still not well understood, and further research is needed to determine its full implications in the development and progression of cancer." (PMID 37171396, 2023). "Additionally, TMC7 could also induce cancer cell proliferation and metastasis in oral tongue squamous cell carcinoma." (PMID 36713450, 2022). "However, the mechanisms of how TMC7 promotes cancer development are still unclarified." (PMID 36713450, 2022). "Further, TMC4, TMC5, TMC6, TMC7, and TMC8 were tissue-specifically and cancer-specifically expressed." (PMID 34899684, 2021). "The results showed that TMC4 and TMC5 have a similar expression pattern in different cancers, as do TMC6 and TMC7." (PMID 34899684, 2021).
TMC7 also shares sentences with these, for which no sentence is quoted: prostate carcinoma (1 paper); rectal cancer (1).